IGF1 (insulin like growth factor 1)
Diseases named in the same sentence as IGF1 in open-access papers (continued):
Sharing a sentence is not in itself a finding about the gene and the disease.
acromegaly (continued). "Neuroendocrine tumours can stain positive for GHRH without coexisting acromegaly, but the resolution of patient symptoms and normalisation of serum GH and IGF1 levels following surgery imply that this was functional secretion." (PMID 24897038, 2014). "In our patient, this appeared not to be necessary, since her IGF-1 levels went down to normal and the development of acromegaly was arrested." (PMID 22273876, 2012). "Acromegaly is a chronic, progressive, and multisystem disease characterized by the hypersecretion of growth hormone (GH), which in turn generates an excessive amount of IGF-1 (insulin-like growth factor-1), which mediates most of the effects of GH." (PMID 23209463, 2012). "Although she had no overt symptoms of acromegaly, her cardiac function was improved when her GH and IGF-1 levels were reduced as she had less dyspnoea." (PMID 20211008, 2010). "In addition, with its higher efficacy in reducing GH and IGF-1 levels compared with fg-SRLs, PAS has shown a detrimental effect on glucose metabolism since early studies on healthy volunteers and clinical trials in patients with acromegaly." (PMID 39859181, 2025). "Furthermore, despite higher baseline IGF-1 levels, the demographic, imaging, metabolic, and prognostic features of patients with PIT1/SF1 tumors were similar to those of patients with PIT1 tumors in the context of acromegaly." (PMID 40421250, 2025). "Before PAS treatment acromegaly was not controlled (i.e., IGF-1 ULN > 1) in 86% of the cohort." (PMID 39841390, 2025). "Among CAM2029-treated patients, it was notable that those who discontinued treatment due to AEs prior to week 22 and were regarded as nonresponders in the primary and secondary analyses had IGF-1 ≤ULN at their final assessment before switching back to their previous treatment for acromegaly." (PMID 39378125, 2025). "However, his IGF-1 (somatomedin-C) levels were found to be low, which ruled out acromegaly and raised questions about potential GH axis abnormalities." (PMID 41552116, 2025). "Laboratory tests showed elevated IGF-1 of 52.3 nmol/mL (12.3-32.9 nmol/L), a nonsuppressible growth hormone (GH) level of 3.8 mcg/L (<0.4 mcg/L) after a 75 g oral glucose tolerance test, confirming acromegaly." (PMID 40201458, 2025). "Regarding in vivo data, an interesting post-hoc analysis of the PAPE study described an increase in T2-weighted MRI signals in treated somatotroph adenomas; patients with these radiological findings exhibited a more pronounced decrease in IGF-1 irrespective of tumour shrinkage." (PMID 39082175, 2025). "Disease activity was determined based on IGF-1 and IGF-1 index levels only, without considering GH suppression tests, which may have influenced the categorization of active and inactive acromegaly patients." (PMID 41302934, 2025). "A second, not mutually exclusive, explanation is that EVin may indicate an abnormal CO2 chemosensitivity resulting from chronic exposure to GH/IGF-1 excess, which could explain the evidence of higher arterial CO2 and bicarbonate levels in patients with acromegaly compared to controls." (PMID 41099943, 2025). "Similarly, other studies have shown increased hepatic steatosis and fibrosis in acromegaly, with 83.8% of newly diagnosed patients presenting an elevated hepatic steatosis index, independent of GH, IGF-1, or metabolic markers." (PMID 40725515, 2025). "On the contrary, in respect of baseline IGF-1 levels, a lower probability of not controlling acromegaly was observed only in patients with baseline IGF-1 value <300 μg/L (ES = 0.24, 95% CI: 0.20–0.29) or between 300 and <500 μg/L (ES = 0.36, 95% CI: 0.32–0.40)." (PMID 38197875, 2024). "Since elevated IGF-1 levels were detected, a 75-g oral glucose tolerance test was performed, which revealed normal GH suppression with GH constantly under 1 ng/mL and nadir under 0.4 ng/mL; the patient had no typical signs or symptoms of acromegaly." (PMID 39217593, 2024).
acromegaly (continued). "Therefore, other factors like lifestyle, diet, and physical activity than GH/IGF-1 levels may play a role in the development of cerebrovascular diseases, mainly AIS, in patients with acromegaly." (PMID 37584889, 2024). "For example, mild acromegaly could exhibit nadir GH < 0.4ng/ml, and the levels of IGF-1 could also be affected by physiological and non-physiological factors." (PMID 39044175, 2024). "As expected, the basal and post-OGTT GH and IGF-1 levels were lower in the absence of acromegaly." (PMID 37344722, 2024). "The patient’s diagnosis of acromegaly, attributed to a pituitary adenoma, was confirmed through clinical observations, laboratory findings (notably raised serum GH and IGF-1 levels, and absence of GH suppression after glucose load during an OGTT), and pituitary MRI scans." (PMID 39331882, 2024). "However, the prevalence of NAFLD in patients suffering from acromegaly and the correlation between elevated IGF-1 levels and NAFLD have not been investigated." (PMID 38370349, 2024). "However, current therapies focusing on the GH/IGF-1 axis are only effective in approximately 28%-50% of patients with acromegaly, while the remaining 50%-72% continue to experience excessive bone growth and/or abnormal bone metabolism, even after GHPA reduction or GH/IGF-1 level normalization." (PMID 36875488, 2023). "However, the prevalence of true carotid plaques was not increased in patientswith acromegaly compared to controls, suggesting that vessels are notsignificantly affected by prolonged excess of GH and IGF-1." (PMID 39076279, 2023). "Interestingly, patients surgically treated for acromegaly who achieved a reduction in serum IGF-1 but not GH levels showed improved glucose tolerance in the OGTT during the early postoperative period." (PMID 37441495, 2023). "Given the small number of laboratories that perform this analysis, and the relatively high cost, the assay for IGF-1 is not performed as part of the routine serum analysis panel at our institution, as it is reserved for cats with clinical suspicion of acromegaly." (PMID 37370445, 2023). "Baseline GH and IGF1 assays add no value to the acromegaly confirmation or surveillance amid pregnancy, but suggestive clinical features and pathological report after hypophysectomy (neurosurgery was postponed after delivery in one case) are prone to acromegaly confirmation." (PMID 36359512, 2022). "IGF-1 synthesis may be hampered by long-term obesity, malnutrition, and prolonged fasting in patients with and without acromegaly." (PMID 36105896, 2022). "In addition, laboratory data to determine biochemical control of acromegaly, such as GH and IGF-1 levels, were not available." (PMID 34973139, 2022). "It should be also emphasized that even if pasireotide-LAR treatment did not result in GH and IGF-1 levels normalization, a significant alleviation of acromegaly-related symptoms such as headache, impaired functioning, fatigue, excessive sweating, joint pain, and paresthesia, was observed." (PMID 34498217, 2022). "Within controlled acromegaly patients, we could not detect a significant relationship between sclerostin levels and parameters reflecting GH/IGF-1 activity." (PMID 34448099, 2022). "However, IGF-1 and GH have more effect on the phosphorus levels in patients with acromegaly rather than hypogonadism." (PMID 35340319, 2022). "The current study shows that GH, IGF-1 and PRL concentration, tumor size and invasiveness, as well as granulation pattern may predict surgical outcome in acromegaly, whereas male sex, GH concentration and granulation pattern may also forecast the response to first-generation SRLs." (PMID 36187106, 2022). "However, as IGF-1 levels in most of these conditions are not elevated, the diagnosis of acromegaly can be excluded." (PMID 33803429, 2021).
acromegaly (continued). "Our case differs from these two published cases in that our patient was not treated with conventional medical therapy for acromegaly; instead, she received initial therapy with anastrozole, which exacerbated her musculoskeletal symptoms, presumably mediated by the effect on her GH/IGF-1 axis." (PMID 33910628, 2021). "For patients with acromegaly who have not achieved biochemical remission after surgery, dopamine receptor agonist therapy is also a treatment options, especially for those patients with only a mildly elevated serum IGF-1 concentration." (PMID 33869029, 2021). "Normalized GH and IGF-1 levels do not always coincide with symptom relief, which may be explained by ‘extra-hepatic acromegaly’." (PMID 32333268, 2020). "For example, the finding that there was a similar prevalence of radiation therapy, repeat surgeries and normal IGF-1 at last follow-up suggests that the patients with acromegaly and PHP did not have a more aggressive clinical course than those with isolated GH-secreting tumors." (PMID 32311048, 2020). "Moreover, the association between blood pressure and IGF-1 levels switched from negative to positive in cohorts with high circulating IGF-1 levels (e.g. acromegaly patients)." (PMID 32458292, 2020). "Medical treatment of acromegaly with the combination of the second-generation somatostatin receptor ligand (SRL) pasireotide long-acting release (PAS-LAR) and the GH receptor antagonist, pegvisomant (PEGV) provides control of insulin-like growth factor I (IGF-1) levels in most (77.0%) patients." (PMID 32333268, 2020). "However, there are other conditions that can mimick the clinical features seen in acromegaly without GH/IGF-1 anomalies, termed as pseudoacromegaly." (PMID 31916215, 2020). "However, some studies indicate that vitamin D concentration does not change significantly with changes in IGF1 and GH levels, as in patients with acromegaly and GHD after treatment." (PMID 30804998, 2019). "However, many studies have shown that radiation dose and tumor volume did not affect the remission rate of acromegaly patients after radiotherapy, but that pre-radiotherapy GH and IGF-1 levels did show significant correlations with radiotherapeutic response." (PMID 31507537, 2019). "Serum concentrations of GH (6.00 ng/ml) and IGF-1 (341 ng/ml) exceeded the normal ranges, but she had no neurological deficit or medical history of hypertension and diabetes mellitus, and no physical characteristics of acromegaly." (PMID 30862315, 2019). "Second, while normal IGF-1 virtually excludes the diagnosis of acromegaly, elevated concentrations of IGF-1 outside puberty and pregnancy strongly support the hypothesis." (PMID 28977166, 2017). "We cannot completely rule out acromegaly in the group of patients with persistently elevated IGF-1, even though 4 of 5 patients had a normal MRI (and one had a normal octreoscan to rule out an ectopic source), but there have been described acromegaly cases without a visible adenoma in the MRI." (PMID 28898247, 2017). "We did not include them in the acromegaly group because we did not have pathological certainty of an acromegaly diagnosis and the findings could have been related to the IGF-1 assay." (PMID 28898247, 2017). "Thus, 7 patients no longer had a diagnosis of acromegaly (based on spontaneous normalization of IGF-1 in 5 and on GH suppression in 2)." (PMID 28977166, 2017). "In a meta-analysis of published studies enrolling patients with acromegaly to receive long-acting somatostatin analogues for at least 3 months’ duration, adjuvant treatment with octreotide LAR achieved GH levels <2.5 μg/L in 57 % of patients and normal IGF-1 in 67 %." (PMID 26290466, 2016). "Similarly, in this study patients with low IGF1 without GH dynamic on provocation tests were also included, despite the fact that in 30–40% there is dissociation between IGF1 and GH values post acromegaly." (PMID 25600246, 2015).
acromegaly (continued). "The initial endocrine evaluation included an elevated serum IGF1 measurement and a subsequent GH profile following an oral glucose load demonstrated a slightly elevated nadir GH level indicative of acromegaly despite the absence of classical symptoms and signs." (PMID 25614825, 2015). "In contrast, although IGF1 levels elevated to approximately three-times normal and showed diffuse robust staining against GH in the adenoma, the patient did not exhibit signs of acromegaly." (PMID 25614823, 2015). "Importantly, patients with pure somatotroph adenomas were significantly more likely to present with abnormal glucose metabolism [48.7%] than those with mixed adenomas [9.7%] [p<0.001] independent of GH/IGF-1 levels or tumor invasiveness." (PMID 24039977, 2013). "Although transsphenoidal craniotomy (TSC) is considered the gold standard intervention for the treatment of acromegaly, it is imperative that the goal of treatment—the restoration of a normal GH secretion profile and normalization of serum IGF-1—not be overlooked." (PMID 22518121, 2012). "Several studies have now reported poorer QoL for acromegaly patients relative to the general population; the direction of evidence from these points to a negative relationship between QoL and IGF-1 levels, but no studies have examined utility gain from PEG treatment." (PMID 19814797, 2009). "We could not include IGF1 or GH levels in the linear regression model, especially for the active acromegaly subjects, as levels at the time of echocardiography were not available for all the patients, and categorization of clinical activity was based on the last available GH/IGF1 levels." (PMID 40091946, 2025). "A limitation in this case is the absence of dynamic growth hormone axis testing, which may have clarified the significance of the mildly elevated IGF-1 level, although the overall clinical picture suggested a non-functioning adenoma with no biochemical evidence of acromegaly." (PMID 41450383, 2025). "Additionally, the identification of hormonal levels (GH and IGF-1) and related anatomical changes enhances our understanding of OSAHS severity, offering valuable evidence on the pathophysiological mechanisms that should be considered when evaluating patients with acromegaly." (PMID 39958072, 2025). "Thus, excess GH/IGF-1 is not the main driver of subclinical atherosclerosis in acromegaly patients." (PMID 37584889, 2024). "However, discordant GH and IGF-1 values with elevated IGF-1 levels but normal GH suppression following OGTT may not exclude acromegaly." (PMID 37543629, 2023). "In female patients, elevated IGF-1 was associated with an increased risk of IVS thickening in the following groups: 18–44 years (OR, 1.018; 95% CI, 1.004–1.039; P < 0.05), 45–59 years (OR, 1.005; 95% CI, 1.002–1.009; P < 0.01), and absence of acromegaly (OR, 1.003; 95% CI, 1.001–1.006; P < 0.01)." (PMID 36568107, 2022). "According to the 2014 Endocrine Society Clinical Practice Guideline on acromegaly, lack of suppression of GH following 75 g OGTT is the gold standard diagnostic test for acromegaly and this should completed as a confirmatory test in patients with elevated or equivocal serum IGF-1 levels." (PMID 33803429, 2021). "Exposure to IGF-1, but not GH, induced trained immunity ex vivo and in vivo, which is likely to account for the augmented ex vivo stimulated cytokine production from monocytes obtained from acromegaly patients, but also in cells obtained from healthy volunteers that are trained with IGF-1 ex vivo." (PMID 32458292, 2020). "Therefore, normal IGF-1 levels adjusted-age effectively excludes the diagnosis of acromegaly." (PMID 31939489, 2019). "Some research has shown that smaller tumors and a higher radiation dose may result in a better radiotherapeutic response, while Lee and colleagues found that higher radiation dose and IGF-1 levels could affect the radiotherapeutic response in acromegaly patients, but that tumor volume did not." (PMID 31507537, 2019).
acromegaly (continued). "Medications for acromegaly are typically indicated for patients that are not surgical candidates or do not wish to have surgery, following subtotal tumor resection, and for patients with persistent elevations in GH and IGF-1 levels that are awaiting the effectiveness of radiation-based treatments." (PMID 22518121, 2012). "Medical therapy of acromegaly is indicated in patients who failed to achieve the current remission criteria, that is, (i) a GH nadir below 1 μg/L during a 75 g oral glucose load, (ii) a normal age- and sex-adjusted IGF-1 concentration either after surgery or following radiotherapy." (PMID 22550484, 2012). "Biochemical tests showed normal pituitary hormone levels, except for mildly elevated insulin-like growth factor 1 (IGF-1) and slightly low thyroid-stimulating hormone (TSH), suggesting a slight growth hormone axis dysfunction without clinical acromegaly." (PMID 41450383, 2025). "In this study, patients with acromegaly and OSAHS had higher GH and IGF-1 levels than those without OSAHS." (PMID 39958072, 2025). "They typically have GH and serum insulin-like growth factor 1 (IGF-1) levels in the reference range and no acromegaly-like symptoms." (PMID 39044175, 2024). "Additional studies likewise suggest that cured acromegaly patients did not achieve better cognitive outcomes compared to patients with uncontrolled hormone production, implying that long-term exposure to excess GH and IGF-1 may have long-term effects on brain function." (PMID 36983284, 2023). "Patients with acromegaly with NAFLD had lower GH, IGF-1, and ANGPTL-8 levels than in those without NAFLD (P = .025, P = .011, and P = .036, respectively)." (PMID 37590020, 2023). "Serum phosphorus and calcium concentrations significantly correlated with IGF-1 levels and SAGIT scores in patients with non-remission acromegaly." (PMID 38137499, 2023). "The main aim of the present study was to characterize a large group of patients presenting with GH/IGF-1 discrepancy (high IGF-1 levels but suppressed GH values according to the most recent guidelines), both with and without an initial suspicion of acromegaly." (PMID 34081617, 2021). "In acromegaly, the tumor produces GH but not IGF-1, and absolute IGF-1 levels or IGF-1 z-scores increase nonlinearly with GH levels, which results in a far greater extent of nonlinearity between GH and IGF-1 levels than has been previously recognized." (PMID 30916168, 2019). "Insulin-like growth factor-1 (IGF-1) and growth hormone (GH) levels are the main targets for monitoring acromegaly activity, but they are not in close relationship with the clinical course of the disease and the associated comorbidities." (PMID 31561638, 2019). "Unlike the pulsatile nature of GH secretion, the IGF-1 level is much more constant throughout the day, thus, the IGF-1 level is being used more frequently for the routine diagnosis of acromegaly." (PMID 30336646, 2018). "One of the consensus groups on acromegaly recently recommended drug treatment combining a long-acting SSA and pegvisomant in patients in whom GH and IGF-1 levels did not decrease with somatostatin agonists alone (around 50% of cases)." (PMID 28490347, 2017). "Furthermore, our patient had high IGF-1 levels, with a normal suppression of GH during OGTT and neither clinical signs of symptoms of acromegaly, nor MRI findings of pituitary adenoma." (PMID 39217593, 2024). "In such a scenario, a long-term observational study could help determine the incidence of new-onset acromegaly in non-acro↑IGF−1 GH-Par subjects and elevated IGF-1 levels." (PMID 37344722, 2024). "In addition, our stratified analysis also suggested that the relationship between IGF-1 and IVS thickening is derived from the patients without acromegaly." (PMID 36568107, 2022).